MYH7 (myosin heavy chain 7)
Diseases named in the same sentence as MYH7 in open-access papers (continued):
Sharing a sentence is not in itself a finding about the gene and the disease.
cardiomyopathy (163 papers, 2006 to 2026). A disease of the heart muscle or myocardium proper. "Genetic analysis revealed two heterozygous missense variants in sarcomeric genes associated with inherited cardiomyopathies: MYH7: c.4186C>T (p.Arg1396Trp) and MYBPC3: c.2672G>A (p.Arg891Gln), both classified as variants of uncertain significance." (PMID 41728227, 2026). "MYH7-induced cardiomyopathy is a complex condition, associated with variable clinical presentation and phenotype." (PMID 40290163, 2025). "A reduced MYH6/MYH7 gene expression ratio is a well-established molecular hallmark of cardiomyopathy and heart failure." (PMID 41295372, 2025). "Cardiologic examinations confirmed the familial nature of cardiomyopathy and the pathogenicity of variant c.542G>T in MYH7 gene." (PMID 40565367, 2025). "We performed GS of 48 individuals with variants in MYH7, the gene encoding beta myosin heavy chain, and a personal or family history of cardiomyopathy." (PMID 40791945, 2025). "We evaluated the utility of GS in combination with cardiac expression data to identify candidate genetic modifiers in a patient cohort initially diagnosed with monogenic cardiomyopathy attributed to variants in MYH7." (PMID 40791945, 2025). "This study reports on a Chinese Han cardiomyopathy family line carrying the MYH7 c.2770G > A (p.Glu924Lys) mutation." (PMID 40670969, 2025). "Under normal conditions, cardiac contraction genes showed minimal changes, but 12-h fasting disrupted Tnni3 and Myh7 expression (linked to cardiomyopathies), which was prevented by rhFGF21 replenishment." (PMID 40998786, 2025). "The D313Y variant, although historically considered benign or a VUS, has recently been associated with hypertrophic cardiomyopathy, particularly when coexisting with mutations in other cardiomyopathy-related genes (e.g., MYH7)." (PMID 41010031, 2025). "A heterozygous deletion variant in the MYH7 gene (NM_000257.4: c.1090T>C, p.Phe364Leu) was discovered through genetic testing using a cardiomyopathy-associated gene panel in the patient and his father and the older brother who had LVNC." (PMID 38540440, 2024). "Myosin-7 (MYH7) encodes the beta-myosin heavy chain, a vital component of the sarcomeric apparatus, and its mutations are extensively linked to cardiomyopathies." (PMID 38559672, 2024). "Mutations in this gene, as well as the neighbouring MYH7 responsible for the β-myosin heavy chain, have been linked to several pathologies: cardiomyopathies, arrhythmias and congenital heart disease (CHD)." (PMID 38523678, 2024). "Pathogenic MYH7 variants cause cardiomyopathies primarily due to decreased (DCM) or increased (HCM) sarcomere force generation." (PMID 38771459, 2024). "Mutations in the MYH7 R403Q in HCM patients result in a particularly severe cardiomyopathy characterized by progressive myocardial dysfunction." (PMID 39465141, 2024). "This is important both for fundamental studies of molecular mechanisms and for investigations of deleterious diseases like cardiomyopathies due to mutations in the MHC gene (MYH7)." (PMID 38928453, 2024). "Four EHI cases had variants in dominantly inherited cardiomyopathy genes, including two with MYH7 variants that affected highly conserved amino acids within myosin S2 and light meromyosin domains of the beta myosin." (PMID 39457051, 2024). "By cardiomyopathy subtype, MYH7 deleterious variants clustered within myosin head and neck regions and TTN truncating variants clustered within the A-band zone in male and female patients." (PMID 37477868, 2023). "For instance, pathogenic variants and rare variants in TTN and MYH7 genes have been reported in patients with chemotherapy-induced cardiomyopathy." (PMID 38202009, 2023). "When analyzed by cardiomyopathy subtypes, MYH7 variants in HCM patients clustered within myosin head and neck regions in both pediatric and adult HCM patients but were rare in the head domain in DCM patients." (PMID 37477868, 2023).
cardiomyopathy (continued). "In this context, it is notable that the age of onset of MYH7-associated cardiomyopathy can be very early in life, including at birth or prenatally, whereas in adult cardiology, patients most commonly present with symptoms during their 3rd and 6th decades." (PMID 35854315, 2022). "A novel missense variant was identified (c.1963C>A:p.Leu655Met) in the MYH7 gene of a rare cardiomyopathy condition called LVNC by using WES analysis, a mutation that affected the MYH7-actin interaction." (PMID 35463789, 2022). "Our gene-based meta-analyses identified a burden of rare coding variants associated with QT, JT, and QRS, in genes typically linked with inherited channelopathies (KCNQ1, KCNH2) and cardiomyopathies (MYH7, TNNI3K)." (PMID 36050321, 2022). "Many studies have shown that its upregulation is one feature of maturation and aging, but MYH7 has been also closely linked to cardiomyopathy." (PMID 33710972, 2021). "Missense mutations are the most prevalent cardiomyopathy-related pathogenic mechanism in MYH7; however, ClinVar reports 20 cases of pathogenic and likely pathogenic truncating variants with various degrees of confidence." (PMID 34691145, 2021). "One variant, p.(Arg1359Cys), was detected in the MYH7-gene, which has been described to be associated with cardiomyopathy." (PMID 32789579, 2021). "Germline mutations with pathogenic or likely pathogenic effects at glycosylation sites are associated with cardiomyopathies (MYH7), cancer predisposition (CDH1), epilepsy (SCN1B), and others." (PMID 33834021, 2021). "Studies of the genetic causes of LVNC have primarily identified variants in cardiomyopathy genes, including MYH7, MYBPC3 and TTN, with reported genetic testing yields between 17 and 41%5." (PMID 33082984, 2020). "It has been shown that TOF is genetically heterogeneous, and a subgroup is characterized by genetic alterations in other sarcomere genes known to be causative of cardiomyopathy, such as MYH7 and MYBPC3." (PMID 33033063, 2020). "Genetic mutations associated with cardiomyopathy play a key role in disease formation, especially the mutation of sarcomere encoding genes and ATP kinase genes, such as titin, lamin A/C, myosin heavy chain 7, and troponin T1." (PMID 30995779, 2019). "A recent study found that approximately one-half of the patients with NCCM had a mutation in a cardiomyopathy gene, and mutations in the MYH7, MYBPC3, and TTN genes were the most prevalent." (PMID 30809538, 2019). "The Inherited Cardiomyopathy VCEP published recommendations for interpretation of variants in MYH7, encoding α (alpha) cardiac myosin heavy chain, a gene associated with multiple forms of cardiomyopathy (dilated, hypertrophic, and restrictive)." (PMID 31783775, 2019). "The CMP-EP created adjusted ACMG/AMP variant classification rules that can be used for all MYH7-associated cardiomyopathies." (PMID 29300372, 2018). "The present paper describes a family with a predominantly systolic cardiomyopathy due to an MYH7 E848G mutation that is characterized by subtle early contractile abnormalities which later lead to overt systolic dysfunction and arrhythmias." (PMID 30623132, 2018). "To confirm the pathogenic role of MYH7 E848G in causing this systolic cardiomyopathy, we strategically chose to knock out MYH7 in a WT iPSC line and then rescue it with MYH7-expressing adenoviruses." (PMID 30623132, 2018). "Recently, several studies reported that MYH7 is associated with cardiac infarction and the development of cardiomyopathy." (PMID 29748547, 2018). "This outcome confirms the pathogenic role of MYH7 E848G in mediating this familial systolic cardiomyopathy and suggests that it is acting as a dominant-negative poison peptide." (PMID 30623132, 2018). "Mutations in the myosin heavy chain 7 (MYH7) gene commonly cause cardiomyopathy but are less frequently associated with congenital heart defects." (PMID 28864942, 2017).
cardiomyopathy (continued). "Defects of the slow myosin heavy chain isoform coding MYH7 gene primarily cause skeletal myopathies including Laing Distal Myopathy, Myosin Storage Myopathy and are also responsible for cardiomyopathies." (PMID 28927399, 2017). "In conclusion, this study describes the first Dutch founder mutation in the MYH7 gene, a mutation associated with CHDs and cardiomyopathies, with frequent childhood onset but a relatively benign course." (PMID 28864942, 2017). "For example, the first initiative tackled by ClinGen’s Cardiovascular Domain Working Group has been modification of the original ACMG–AMP recommendations specifically for classification of MYH7 variants for cardiomyopathy." (PMID 27324065, 2016). "Cardiomyopathy mutations are commonly found in the myosin heavy chain 7 gene (MYH7) encoding human β-cardiac myosin heavy chain (M2β), which is the motor that drives contraction of the ventricular myocardium." (PMID 28119616, 2016). "Although numerous mutations in MYH7 are known to be associated with cardiomyopathy, in recent years CHDs have also been linked to this gene." (PMID 22955375, 2013). "Cardiac involvement is usually not a feature of Laing distal myopathy but there are a few exceptions with diseases associated with MYH7 mutations and presenting with distal myopathy as well as cardiomyopathy." (PMID 22918376, 2013). "Nevertheless, cases of MPD1 caused by mutations out of this range are reported, as an example in MYH7 exon 40, or a case of distal myopathy caused by a MYH7 exon 16 mutation in the head of myosin showing associated cardiomyopathy." (PMID 23153285, 2012). "ZFHX3 also interacts with MYH7 (myosin, heavy chain 7, cardiac muscle, beta, NP_000248), in which mutations are known to cause an inherited form of cardiomyopathy." (PMID 19132087, 2009). "In April 2024, the ClinGen Cardiomyopathy Variant Curation Expert Panel (VCEP) adapted the ACMG/AMP criteria for eight of the sarcomeric genes (MYH7, MYBPC3, TNNI3, TNNT2, TPM1, ACTC1, MYL2, and MYL3), providing a refined framework for variant interpretation in these genes." (PMID 41357762, 2025). "In this study, the pathogenicity of the MYH7 c.2770G > A (p.Glu924Lys) mutation was confirmed for the first time in a Chinese polyphenotypic cardiomyopathy family line, thereby revealing its clinical features leading to significant phenotypic heterogeneity and a propensity for rapid progression." (PMID 40670969, 2025). "This study utilized clinical phenotyping and whole exome sequencing of a multigenerational cardiomyopathy family line, revealing that the c.2770G > A (p.Glu924Lys) mutation in the MYH7 gene was significantly associated with HCM and RCM phenotypic heterogeneity." (PMID 40670969, 2025). "The study hypothesises that the MYH7 c.2770G > A mutation can lead to transgenerational and multisubtype cardiomyopathy phenotypic heterogeneity, and that the mechanism may be related to transcriptional regulation and epigenetic modifications." (PMID 40670969, 2025). "Proteins linked to cardiomyopathy include Myosin-7 (MYH7) and Tropomyosin 3 (TPM3)." (PMID 38787940, 2024). "MYH7 mutations are reported in 14–25% of all cardiomyopathy cases." (PMID 37794383, 2023). "TTN truncating variants have been suggested to cause 25% of DCM, and the MYH7 gene, related to sarcomeres, may be present with a spectrum of phenotypical cardiomyopathies [HCM, DCM])." (PMID 36005429, 2022). "The studies revealed that MYH7 gene mutations could cause skeletal muscle disease or skeletal muscle disease with cardiomyopathy." (PMID 36313432, 2022). "Several mutations in MYH7 have been associated with inherited cardiomyopathies and muscle atrophy." (PMID 34357026, 2021).
cardiomyopathy (continued). "Mutations (more than 200) in the MYH7 gene are usually associated with several structural Cardiomyopathies, such as Hypertrophic (HCM; MIM 192600), Restrictive (RCM), Dilated (DCM; MIM 115200), or Left Ventricular Non-Compaction (LVNC; MIM 613426), as well as myosin storage myopathy (MIM 608358)." (PMID 34067482, 2021). "Importantly, Shah, D. gave an outstanding article about these two methods of silencing as therapeutic treatment for MYH7 gene mutation cardiomyopathy." (PMID 34977015, 2021). "Together, vmhcl/myh7 loss of function is sufficient to induce cardiomyopathy in zebrafish." (PMID 34935644, 2021). "Mutations of myh6 and myh7 in zebrafish are known to be associated with cardiomyopathy." (PMID 34775978, 2021). "The MYH7 p.Leu1533Pro variant in a distal myopathy patient (S.7) was positioned in the distal rod region of the protein where other mutations have been established to cause Laing distal myopathy and cardiomyopathies." (PMID 34103343, 2021). "We further examined the expression of molecular marker genes and found that the expression of brain natriuretic peptide (Nppa) and beta-myosin heavy chain (β-MHC, encodes by Myh7), molecular markers of cardiomyopathy, was reduced 2 months after miR-19a/19b injection." (PMID 30996254, 2019). "Therefore, the role that MYH7 mutations play in the onset of different cardiomyopathy phenotypes is unclear." (PMID 30650640, 2019). "We also investigated the expression of Nppb and Myh7, two markers associated with cardiomyopathies and cardiac pathology, which may be indicators of higher risks of heart failure in the MPS II mouse model." (PMID 29884617, 2018). "Interestingly, and despite the young age of onset of cardiomyopathy, this MYH7 mutation appears to result in only mild to moderate clinical symptoms." (PMID 28864942, 2017). "Alterations in human MYH7 (OMIM: 160760) are associated with cardiomyopathies." (PMID 26815362, 2016). "An additional mutation (MYH7-p.Arg1045His) was found in family B in patients II: 1 and II: 3; the proband (family B, II: 3) with the doubly heterozygous mutations displayed a more malignant clinical phenotype of cardiomyopathy." (PMID 26199943, 2015). "In addition to classic HCM, MYH7 mutations may cause cardiomyopathies with different heart morphology and function, such as dilated cardiomyopathy (DCM) and HCM with features of restrictive cardiomyopathy (RCM)." (PMID 33033063, 2020). "Hypertrophic (HCM) and dilated (DCM) cardiomyopathies are heart muscle diseases caused by variants in genes encoding sarcomere proteins, most commonly MYH7 (encoding cardiac β-myosin heavy chain; MHC) and MYPBC3 (encoding MyBP-C) and rarely in MYL2 and MYL3 that encode the ELC and RLC, respectively." (PMID 28606303, 2017). "An associated cardiomyopathy has not been reported in typical CCD due to mutations in the RYR1 gene; however, cardiomyopathies associated with mutations in the MYH7 and the ACTA1 genes may feature central cores on muscle biopsy but do not share the typical clinical features of CCD." (PMID 17504518, 2007). "Since the identification of pathogenic variants in MYH7 as a genetic cause of HCM in 1990, enormous progress has been made in understanding genetic factors contributing to cardiomyopathies." (PMID 40207042, 2025). "Terms related to cardiomyopathy are enriched in genes of the foetal gene programme (Acta1 and Myh7) and sarcomere genes." (PMID 41032675, 2025). "Given the clinical pathomechanistical overlap with other cardiomyopathies, such as HCM, additional core genes that are associated with DCM include MYH7, MYBPC3, TNNC1, TNNT2, and TPM1." (PMID 40207042, 2025). "This has also been reported for other heterozygous cardiomyopathy gene models, such as Csrp3, Mybpc3, Myh7 and Ttn displaying phenotypes in homozygous settings only, whilst heterozygous animals showed no cardiac abnormalities." (PMID 40128237, 2025).
cardiomyopathy (continued). "Beyond these classical sarcomeric mutations, MYH7 variants are also implicated in 40% of congenital HCM cases, and both MYH7 and MYBPC3 have been linked to other cardiomyopathies such as dilated cardiomyopathy (DCM) and left ventricular non-compaction (LVNC)." (PMID 40426840, 2025). "The rationale behind this CRISPR technique, is that MYH7 cardiomyopathy exerts a dominant negative effect on cardiac contractility, and CRISPR is meant to suppress the defective allele." (PMID 40371062, 2025). "We observed significant associations with individual cardiomyopathy genes, finding that mitral annular plane systolic excursion associated with TTN and TNNT2, and LA pump volume and RA-EF associated with MYH7." (PMID 40660250, 2025). "Molecular evidence of cardiomyopathy, including inflammation marker (Tnd and Il6), fibrosis marker (Col1a1 and Col3a1), and hypertrophy marker (Nppa, Nppb, and Myh7), significantly increases when Rab7 was knocked out." (PMID 38837607, 2024). "There is an increased prevalence of rare variants (BAG3, LMNA, MYH7, TCAP, TNNT2, and TTN), particularly TTNtv, in adult and pediatric cancer patients with cancer therapy-induced cardiomyopathy." (PMID 39070560, 2024). "Patients with the PLN variant exhibited higher incidences of non-sustained ventricular arrhythmias compared to those with myosin-binding protein C3 (MYBPC3)/myosin heavy chain 7 (MYH7)-related cardiomyopathies." (PMID 39507141, 2024). "A disruption in these results, for example, by mutations in MYH7 and TTN, results in cardiomyopathies." (PMID 39202774, 2024). "After the identification of pathogenic variants in the myosin heavy chain 7 (MYH7) gene and the cardiac alpha-actin (ACTC1) gene in developing HCM and DCM, respectively, over 100 genes have been reported to cause cardiomyopathies." (PMID 37752589, 2023). "The function of hub genes Tnnt2 and Myh7 have all been discussed in regard to cardiomyopathy and skeletal muscle myopathy." (PMID 37888673, 2023). "Kyoto Encyclopedia of Genes and Genomes (KEGG) result indicatedthat Myh7 is involved in myocarditis, cardiomyopathy, and cardiac musclecontraction." (PMID 39077026, 2023). "There was an excess burden of splice-disrupting variants in PKP2 (5.9%), FLNC (2.7%), TTN (2.8%), MYBPC3 (8.2%) and MYH7 (1.3%), in distinct cardiomyopathy subtypes, and KCNQ1 (3.6%) in long QT syndrome." (PMID 37821546, 2023). "The VEC and VAC models in zebrafish are amenable to both efficient genetic and chemical genetic tools, offering a rapid in vivo platform for discovering candidate signaling pathways of MYH7 cardiomyopathy." (PMID 34935644, 2021). "Five genes account for the majority of genetically explained cardiomyopathy and long QT (MYH7, MYBPC3, KCNQ1, KCNH2, SCN5A), resulting in narrower prediction confidence intervals." (PMID 33046849, 2021). "The sarcomere genes such as MYH7 and MYBPC3 are known to be causative for hereditary cardiomyopathies." (PMID 33928132, 2021). "In summary, this study established zebrafish as a vertebrate model for studying MYH7 cardiomyopathy." (PMID 34935644, 2021). "Molecular marker analyses demonstrated a significant decrease in the expression of the hypertrophic and cardiomyopathy marker genes Nppa, Nppb, and Myh7/Myh6 in AAV-LncHrt-treated hearts." (PMID 34379189, 2021). "In our study, patients with sensorineural hearing loss, seizures, epileptic encephalopathy and cardiomyopathy showed mutations in LOXHD1, KCNQ1, KCNQ2 and MYH7 genes." (PMID 33484326, 2021). "Since the discovery of pathogenic variants in the myosin heavy chain 7 (MYH7) gene in HCM and in the cardiac alpha-actin (ACTC1) gene in dilated DCM, more than 100 causative genes have been reported to be causal for cardiomyopathy." (PMID 34830403, 2021). "MYH7 and TNNT2 encode sarcomeric proteins, essential for contraction and relaxation of the heart muscle, and mutations in these genes have been linked to cardiomyopathy." (PMID 33172956, 2021).